MMP2 (matrix metallopeptidase 2)
Diseases named in the same sentence as MMP2 in open-access papers (continued):
Sharing a sentence is not in itself a finding about the gene and the disease.
melanoma (continued). "Furthermore, another study demonstrated that the overexpression of MMP-2 and MMP-9 in melanoma cells is associated with increased tumor invasiveness and poor prognosis." (PMID 39200315, 2024). "In our study, we show that GH increases MMP2 in melanoma-derived exosomes." (PMID 39123364, 2024). "Additionally, luteolin inhibited proliferation, invasion, and metastasis in A375 melanoma cells by downregulating MMP2 and MMP9 and upregulating TIMP-1 and TIMP-2 expression levels." (PMID 40066127, 2024). "Additionally, GH stimulation leads to the upregulation of N-cadherin and MMP2 in melanoma-derived exosomes, with N-cadherin being transferred to treatment-naïve melanoma cells, enhancing their migratory potential." (PMID 39123364, 2024). "Moreover, matrix metalloproteinase-2 (MMP-2), one of the proteases related to an invasion of tumor cells, was increased in melanoma cells cultured on the EP-coated dishes." (PMID 38674144, 2024). "Moreover, the downregulation of mmp2 and rpsa by chelidonine highlights another crucial aspect of melanoma pathology—the degradation of the extracellular matrix (ECM), which is a key step in tumor invasion and metastasis." (PMID 39598801, 2024). "Additionally, we showed that the protein levels of N-cadherin and MMP2 are elevated in the presence of GH treatment in parent melanoma cells (Malme-3M and SK-MEL-28)." (PMID 39123364, 2024). "Interestingly in melanoma, the pro‐invasive role of MMP2 is stimulated by adipocytes, fostering its hyperactivity." (PMID 38775220, 2024). "Vimentin, SNAL1, and MMP2 are essential genes for melanoma EMT." (PMID 39135915, 2024). "Our studies showed that an Integrin/VE‐cadherin/EphA2/PI3K/MMP‐2 axis could potentially regulate VM formation in melanoma." (PMID 39036079, 2024). "In the GEO database, high MMP2 expression predicts a lower immunotherapy response rate in melanoma and may serve as a predictor for immunotherapy." (PMID 36788565, 2023). "This suggested a potential prognostic value of MMP2 expression with melanoma immunotherapy." (PMID 36788565, 2023). "Finally, it has been reported that integrin β3 expression in lung carcinoma cells is required for the ECM degradation by invadopodia and that active MMP-2 colocalizes with integrin αvβ3 at the melanoma cell surface." (PMID 37312227, 2023). "This suggests that MMP2 plays a vital role in the regulation of CAFs infiltration, potentially participating in immunotherapy response, and thus representing a valuable target of immunotherapy in melanoma." (PMID 36788565, 2023). "GPLG is one of the recognition sequences of the matrix metalloproteinase 2 (MMP-2), which is co-localized on the cell surface with the integrin αVβ3 receptor and is overexpressed in tumors, such as glioblastoma and malignant melanoma." (PMID 37492088, 2023). "For melanoma cells, AuNPs (15 nm) were observed to inhibit the migration, causing the reverse of epithelial-mesenchymal transition (EMT) and reducing angiogenesis by regulating metalloproteinase-2 (MMP-2), c-Myc, and zonula occludens-1." (PMID 37373007, 2023). "In addition to their role in promoting invasion and metastasis, MMP-2 and MMP-9 have also been implicated in other aspects of melanoma progression." (PMID 37504268, 2023). "Moreover, the treatment of the melanoma cells with the mimetic AnxA1 N-terminal peptide Ac2–26 stimulated the invasiveness by increasing MMP-2 expression, depending on FPR/MAPK/STAT3 activation pathways." (PMID 36766767, 2023). "MMP-2 is overexpressed in many types of cancer, including bladder, breast, bronchopulmonary, cervical, colon, glioma, laryngeal, lung, melanoma, myeloma, esophagus, ovary, pancreas, prostate, skin, and stomach cancer." (PMID 37513440, 2023). "Moreover, upregulation of MMP-2 has been described in multiple highly aggressive melanoma cell lines." (PMID 38069171, 2023). "Finally, we evaluated the efficacy of MMP2 inhibitor on CAFs infiltration and immunotherapy using a mouse melanoma model." (PMID 36788565, 2023).
melanoma (continued). "Moreover, previous studies showed that AnxA1 stimulated MMP-2 activity by interaction with FPRs, increasing cell invasiveness and promoting the proliferation and migration of melanoma cells in vitro." (PMID 36766767, 2023). "Next, given prior reports that AhR activation induces MMP2 in melanoma, we evaluated whether it might correlate with Mmp2 expression in these skin samples." (PMID 35316219, 2022). "To conclude, the increase of PCDH9 could suppress melanoma cells by observing the deregulation of MMP2, MMP9, and RAC1." (PMID 36452505, 2022). "This suggested that MMP-2 alone did not cause the direct disruption mediated by the melanoma cells, even though there was evidence that it was most abundantly expressed." (PMID 36005056, 2022). "Conclusively, this study indicates that MMP-2 plays a role in Adriamycin resistance in melanoma mediated by p-ERK1/2 and thus targeting MMP-2/ERK1/2 may be a new targeted therapy for melanoma patients." (PMID 35586209, 2022). "Indeed, cocultivation of fibroblasts and melanoma cells has resulted in MMP-2 high overexpression, whereas; keratinocytes and BCC cells cocultivation led to a moderate upregulation of MMP-2 expression." (PMID 35572966, 2022). "A study on melanoma brain metastases found that astrocytes can produce interleukin (IL)-3, CD40L, CXCL 12, interferon-γ, and other cytokines that stimulate melanoma cells; in this context, IL-23 stimulates tumor cells to produce MMP-2, thereby promoting tumor cell proliferation." (PMID 36338717, 2022). "Moreover, we have noted that metastatic melanoma led to a higher activity of MMP2 in CAFs than fibroblasts cultured in the presence of melanoma derived from primary tumors." (PMID 35538545, 2022). "Another mechanism is mediated by matrix metalloproteinase-2 (MMP2) in the context of melanoma." (PMID 36104718, 2022). "MMP2 also plays a role in skin cancer, as B16 melanoma cells that express MMP2 have slower kinetics in Tlr2−/−Tlr4−/− mice, which suggests that MMP2 overexpression could contribute to tumor growth." (PMID 36624735, 2022). "Malyarenko and colleagues (2019) also conducted a study that demonstrated for the first time the ability of sulfated laminaran from the brown alga Dictyota dichotoma to significantly increase the inhibitory effect of X-rays on SK-MEL-28 melanoma cell migration by regulating MMP-2 and MMP-9 activity." (PMID 35621924, 2022). "Hence, mulberry anthocyanins showed an inhibitory effect on B16F10 melanoma in C57BL/6 mouse model by reducing the MMP-2 and MMP-P expressions." (PMID 35458783, 2022). "MMP-9 (gelatinase B), similar to MMP-2, is present in melanoma both in tumor cells and stroma." (PMID 34360915, 2021). "Furthermore, it was indicated that the increased cell proliferation, migration, and invasion arising under the influence of adipocytes-conditioned medium was connected to the elevated activity of matrix metalloproteases MMP9 and MMP2 in melanoma cells." (PMID 33430277, 2021). "We can also mention the case of the C–O–C type biflavone ochnaflavone which inhibits MMP-9 secretion in human aortic smooth muscle cells through the transcription factors NFκB and AP-1 or a derivative of agathisflavone which suppresses MMP-2 expression and reduces metastasis of melanoma cells." (PMID 33534099, 2021). "Thus, the reduction of this population in Mmp2-OE tumors highlights the detrimental role that overexpression of Mmp2 has in the melanoma TME and explains the overt tumor growth." (PMID 34032639, 2021). "Zhu and colleagues showed that H19 promotes the proliferation, invasion, and growth of melanoma cell line A375 by upregulating Akt phosphorylation, increasing the expression of matrix metalloproteinases 2 (MMP2), MMP9, and Slug and downregulating the expression of E-cadherin." (PMID 34977037, 2021). "One possibility is that, in the context of tumors (like melanoma), the full-length MMP2 protein might be secreted via exosomes from tumor or stromal cells." (PMID 34032639, 2021).
melanoma (continued). "To address how MMP2 mechanistically modulates tumor growth, we adopted murine models of melanoma." (PMID 34032639, 2021). "Maspin decreased lung metastasis in melanoma by inhibiting MMP-2 expression and activity." (PMID 34207884, 2021). "But the effect is not specific to colon cancer cells because much the same activity was reported using A375 and B16 melanoma cells, with an inhibition of cell proliferation, induction of caspase-dependent apoptosis and inhibition of cell migration due to inhibition of MMP-2 and MMP-9." (PMID 33534099, 2021). "mEHT induced the upregulation of the chemoattractant CXCL11 and increased the expression of the matrix metalloproteinase MMP2 which could account for the NK-cell attraction into the treated melanoma." (PMID 33732640, 2021). "Regarding MMP expression, there is a study that relates MMP-2 to RAC1 in melanoma cells." (PMID 34827551, 2021). "To shed light onto this, we investigated MMP2’s function in murine melanoma." (PMID 34032639, 2021). "Thus, reduced expression levels of MMP-2 in melanoma cells resulted in the inhibition of IL-23-induced invasiveness." (PMID 33466236, 2021). "Importantly, brain-metastasizing melanoma cells can reprogram astrocytes to express the pro-inflammatory cytokine IL-23, which upregulates MMP-2 levels to facilitate melanoma cell migration and invasion into the brain parenchyma." (PMID 33466236, 2021). "In addition, although Mmp-2 and Mmp-9 are known to play important roles in the migration and invasion processes of melanoma, Mmp-14 can activate both." (PMID 34207144, 2021). "We next evaluated MMP2 expression in melanoma using B16 F1 and F10 murine melanoma cells." (PMID 34032639, 2021). "Treatment with HA was reported to increase expression and secretion of MMP2 in melanoma cells." (PMID 33958632, 2021). "One mechanism by which OPN can promote metastasis in melanoma is through activation of MMP-2." (PMID 33203146, 2020). "For example, in human melanoma cells with expressed integrin αvβ3, the degradation of type I of collagen by MMP-2 may reveal a binding site with integrin αvβ3 in these cells." (PMID 33198257, 2020). "Melanoma associated fibroblast are also able to remodel the ECM by MMP-1, MMP-2, MMP-13, and MT1-MMP (MMP-14) secretion, which could influence the motility and invasiveness of melanoma cells." (PMID 32984031, 2020). "The p38 MAPK pathway also increased the invasion of malignant melanoma cells through upregulation of matrix metallopeptidase (MMP-2) expression, indicating that inhibition of p38 MAPK may block signaling cascades related to melanoma metastasis." (PMID 32340351, 2020). "Similar research showed that in melanoma, MMP-2 imbalance can be caused by inhibiting TFAP2, which would not promote the oncogenicity." (PMID 32369495, 2020). "We also investigated the correlation of the seven prognostic-associated TBCs between MMP-related genes (MMP2, MMP9, MMP7, MMP14, BSG, EGFR, MMP1, MMP3) and EMT-associated genes (TWIST1, VIM, CDH2, ACTA2, ZEB1), which also indicated a central role of TBCs in melanoma." (PMID 33194704, 2020). "Similarly, luteolin has been found to reduce the proliferation, migration, and invasion of human melanoma cells by suppressing the expression of MMP-2 and MMP-9 and altering the PI3K/AKT signaling pathway." (PMID 32224968, 2020). "Additionally, it was reported that increased WNT5A signaling, which is known to promote melanoma metastasis, induced a Ca2+-dependent release of exosomes containing the pro-angiogenic VEGF and MMP2 factors in melanoma cells." (PMID 32709086, 2020). "Relative to the control (100%), vitamin D at 0.0002, 0.002, 0.02, and 0.2 μM significantly inhibited MMP-1 protein levels to 76%, 69%,77%, and 78% of control (p < 0.05); and significantly inhibited MMP-2 protein levels to 65%, 46%,45%, and 33% of control (p < 0.05), in melanoma cells." (PMID 32150881, 2020).
melanoma (continued). "The PPI network analysis revealed that 6 hub genes, comprising Itgb2, Wdfy4, Itgam, Cybb, Mmp2, and Parp14, might be key candidate genes related to the pathogenesis of melanoma." (PMID 33679872, 2020). "In addition, to validate the regulation of PD-L1 expression through MMP2/9, we generated the stable overexpression (OE) MMP2 or MMP9 melanoma cell lines." (PMID 32988398, 2020). "Besides the impairment of cancer cell motility, our results showed a significant decrease of active MMP2 in the conditioned media of the melanoma cells in vitro." (PMID 33375117, 2020). "Interestingly, CSPG4 has been shown to facilitate assembly of a ternary complex consisting of pro-MMP2, MMP-cleaving enzyme (MT3-MMP), and the proteoglycan itself at the cell surface of melanoma cells, leading to cleavage and thus activation of MMP2." (PMID 32984308, 2020). "Vitamin D inhibited TGF-β, and VEGF at the protein and mRNA levels, suggesting transcriptional mechanism, and MMP-1, and MMP-2 at the proteins level, suggesting post-transcriptional mechanism; and its effectiveness in inhibiting angiogenic and metastatic potential in melanoma cells." (PMID 32150881, 2020). "A recent study in melanoma has also shown α-SMA+ CAF-derived MMP2 may cleave two ligands of the NK-activating receptor at the surface of tumor cells and consequently reduce the NKG2D-dependent cytotoxicity against melanoma tumor cells." (PMID 31462327, 2019). "Additionally, the protein expression levels of metastasis-associated genes (such as MMP2/9, ICAM-1 and VCAM-1) in melanoma cells were suppressed by CLQ treatment." (PMID 31138783, 2019). "In addition, cross-talk between MT1-MMP, MMP-2, and laminin-5γ2 chain fragments contributes to the vasculogenic mimicry of melanoma cells." (PMID 31921634, 2019). "Interestingly, upregulation of MMP2 and MMP9 was linked with the depletion of nestin, a protein postulated as a melanoma stem cell marker, which was also observed in our research model." (PMID 31877948, 2019). "In melanoma, Wnt5a was associated with the release of IL-6, VEGF, and MMP2." (PMID 31510045, 2019). "The hYSK1-mediated loss or downregulation of p16INK4a has been shown to result in an increase in the expression of MMP-2 through transcriptional activation of SP-1, and in the enhancement of the migration and invasion of tumor cells including those of the melanoma and fibrosarcoma." (PMID 30646538, 2019). "Besides this, many human tumors including glioblastomas, melanomas, breast, and colon cancer show upregulated MMP-2 activity." (PMID 29466303, 2018). "Our results demonstrated that bornyl cis-4-hydroxycinnamate is a potentially useful agent that inhibits melanoma cell migration and invasion, and altered melanoma cell metastasis by reducing MMP-2 and MMP-9 expression through inhibition of the FAK/PI3K/Akt/mTOR, MAPK, and GRB2 signaling pathways." (PMID 30042328, 2018). "Particularly, high levels of MMP-2 were observed in WM793 melanoma cell line from the primary VGP." (PMID 29492694, 2018). "In addition, casticin was found to suppress the migration and invasion ability of human melanoma cells by down-regulating MMP-2 and NF-κB p65 expression." (PMID 30401729, 2018). "CXCL1 from primary melanoma cells, B16, might inhibit the MMP2 activity of metastatic melanoma cells, B16F10." (PMID 30123429, 2018). "High protein levels of metalloproteinase MMP-2 were found in all examined melanoma cell lines." (PMID 29492694, 2018). "CD44 and MMPs MMP2 and MMP9 are implicated in the progression and metastasis of melanoma." (PMID 30157785, 2018). "Moreover, activated STAT3 in melanoma can directly combine to matrix metalloproteinase-2 (MMP-2) gene promoter to increase the expression of MMP-2." (PMID 29348670, 2018). "Similarly to other publications, this study showed a high level of the MMP-2 activity in all tested melanoma cell lines." (PMID 29492694, 2018).
melanoma (continued). "MMP-2 and MMP-9 are linked to VM and poor prognosis in cancers of the breast, ovaries, prostate, liver, stomach and kidneys, along with GISTs, mesothelial sarcomas, rhabdomyosarcomas and melanomas." (PMID 27034014, 2017). "We next examined if ANGPTL4 down-regulation in melanoma cells affects MMP-2 secretion." (PMID 29100268, 2017). "Expression of αvβ3 correlates with activation of MT1-MMP and MMP-2 in human melanoma cells." (PMID 29163031, 2017). "The results indicate the combination of two inhibitors could induce MET in melanoma cells and decrease the expression of MMP-2/MMP-9." (PMID 28865485, 2017). "Considering the function of Rictor in mTORC2 and the PI3K/AKT pathway, we hypothesize that Rictor may regulate the phosphorylation and activation of AKT to affect VM by regulating the expression and activation of MMP‐2/9 in melanoma." (PMID 28699701, 2017). "Up-regulation of MMP2 has been previously tied to melanoma invasion as it was shown to be upregulated in highly metastatic human melanoma cell lines and strong MMP2 expression significantly correlates with advanced metastatic disease and worse overall survival." (PMID 27598148, 2016). "Furthermore, MT1-MMP cleaves a wide range of ECM components, promote tumor development and invasion, and activate pro-MMP-2 on the surface of melanoma cells." (PMID 27271600, 2016). "For instance, melanoma cells released pro-angiogenic factor IL-6, vascular endothelial growth factor (VEGF) and MMP2, in a Wnt5a-dependent manner, and co-culture of Wnt5a-silenced melanoma cells with ECs showed decreased EC branching, compared with control melanoma cells." (PMID 27608847, 2016). "In addition to angiogenesis, under hypoxic conditions, HIF-1α plays an important role in the metastatic progression of melanoma by enhancing the expression of MMP such as MMP-2, MMP-9, and MMP-14." (PMID 27271600, 2016). "Furthermore, there was a significant positive correlation between NRP1 and MMP2 expression in melanoma biopsies, and their concomitant expression was inversely correlated with the survival of patients with melanoma." (PMID 25954957, 2015). "The melanoma cell lines showed different growth patterns in the brain, and these differences were associated with differences in expression of the angiogenic factors VEGF-A and IL-8 and the matrix metalloproteinases MMP-2 and MMP-9." (PMID 26667022, 2015). "In a previous study, we revealed that A-07, D-12, and T-22 melanoma cells cultured at acidic extracellular pH show increased secretion of MMP-2 and MMP-9, enhanced invasiveness in vitro, and enhanced potential to develop experimental pulmonary metastases in BALB/c nu/nu mice." (PMID 26667022, 2015). "Since both MMP2 and LIFr could influence primary melanoma patient survival, and up-regulation of MMP2 plays a crucial role in melanoma cell migration, we investigated the correlation between MMP2 and LIFr expression." (PMID 26329521, 2015). "BRAF and MMP2 proteins showed a progressive increase from Stage I to Stage IV, whereas Tip60 loss is most pronounced in metastatic melanoma (Stage III and IV) as compared to primary melanomas (Stages I and II)." (PMID 25784655, 2015). "Furthermore, in transgenic MT/RET mice characterized by the development of MT-overexpressing malignant melanomas, an increase in MMP2 and a decrease in TIMP2 expression has been noted." (PMID 25933064, 2015). "Among 123 patients with Stage II melanoma, we performed confirmation analyses for MMP2." (PMID 25784655, 2015). "Furthermore, an MCAM antibody decreases melanoma cell invasion, tumor vascularization, matrix metalloproteinase-2 (MMP-2) expression and reduces formation of lung metastasis in nude mice." (PMID 26703751, 2015). "Here, we demonstrate that inhibition of GLUT1 inhibition lowers MMP2 expression in melanoma cells." (PMID 26293674, 2015). "MMP2, or gelatinase A, which digests primarily type IV collagen, is hypothesized to be involved in melanoma progression." (PMID 25954957, 2015).